RN7SKP157 (RN7SK pseudogene 157)
Gene: Miscellaneous RNA gene on chromosome 5 (62,146,665 to 62,146,946, forward strand). Ensembl gene ENSG00000251983.
Homologues: Orthologues: chimpanzee 7SK (99% identical), mouse Gm55516 (43% identical), guinea pig 7SK (39% identical). Paralogues in human: RN7SKP162 (57% identical), RN7SKP217 (57% identical), RN7SKP294 (57% identical), RN7SKP47 (56% identical), RN7SKP225 (56% identical), RN7SKP133 (55% identical), RN7SKP153 (55% identical), RN7SKP296 (54% identical), RN7SKP79 (54% identical), RN7SKP170 (54% identical), RN7SKP184 (54% identical), RN7SKP90 (54% identical), and 283 more.